NPHP1 (nephrocystin 1)
Description:
Together with BCAR1 it may play a role in the control of epithelial cell polarity (By similarity). Involved in the organization of apical junctions in kidney cells together with NPHP4 and RPGRIP1L/NPHP8 (By similarity). Does not seem to be strictly required for ciliogenesis (By similarity). Seems to help to recruit PTK2B/PYK2 to cell matrix adhesions, thereby initiating phosphorylation of PTK2B/PYK2 and PTK2B/PYK2-dependent signaling (By similarity). May play a role in the regulation of intraflagellar transport (IFT) during cilia assembly. Required for normal retina development (By similarity). In connecting photoreceptor cilia influences the movement of some IFT proteins such as IFT88 and WDR19. Involved in spermatogenesis (By similarity).
Synonyms: NPH1; JBTS4; SLSN1
Tractability: PROTAC: ubiquitination databases record sites on it.
Gene: Protein-coding gene on chromosome 2 (110,122,311 to 110,205,066, reverse strand). Ensembl gene ENSG00000144061.
Subcellular location: Cell junction; Cell junction, adherens junction; Cell projection, cilium; Cytoplasm, cytoskeleton, cilium axoneme; Cell junction, tight junction
Pathways (Reactome):
Organelle biogenesis and maintenance: Anchoring of the basal body to the plasma membrane
Gene Ontology:
Molecular function: protein binding; structural molecule activity
Biological process: positive regulation of bicellular tight junction assembly; actin cytoskeleton organization; cell projection organization; cell-cell adhesion; protein localization involved in establishment of planar polarity; protein localization to ciliary transition zone; retina development in camera-type eye; signal transduction; spermatid differentiation; visual behavior
Cellular component: cell-cell junction; motile cilium; anchoring junction; ciliary transition zone; cilium; cytoplasm; cytosol; membrane; NPHP complex; photoreceptor connecting cilium; adherens junction; axoneme; bicellular tight junction
Genetic constraint (gnomAD): Loss-of-function variants: 40 observed, 56.63 expected, observed/expected ratio (o/e) 0.71, 90% interval 0.55 to 0.92. The upper end of that interval is the gene's LOEUF score, 0.92, which puts it in group 3 of 6, group 1 being the genes least tolerant of losing a copy. Missense variants: 457 observed, 497.14 expected, observed/expected ratio (o/e) 0.92, 90% interval 0.85 to 0.99. Synonymous variants: 153 observed, 175.16 expected, observed/expected ratio (o/e) 0.87, 90% interval 0.76 to 1.
Gene-disease validity (ClinGen):
ClinGen rates the evidence that NPHP1 causes each of these diseases.
nephronophthisis 1 (autosomal recessive): Definitive.
Homologues: Orthologues: macaque NPHP1 (96% identical), chimpanzee NPHP1 (95% identical), dog NPHP1 (85% identical), rabbit NPHP1 (84% identical), pig NPHP1 (83% identical), rat Nphp1 (81% identical), mouse Nphp1 (80% identical), guinea pig NPHP1 (77% identical), tropical clawed frog nphp1 (57% identical), zebrafish nphp1 (47% identical), Caenorhabditis elegans nphp-1 (22% identical).
Diseases named in the same sentence as NPHP1 in open-access papers:
NPHP1 is named in the same sentence as 70 diseases in open-access papers, as found by Europe PMC text mining. Sharing a sentence is not in itself a finding about the gene and the disease. The quoted sentences say what the papers report.
nephronophthisis (39 papers, 2005 to 2025). Progressive tubulointerstitial injury, inherited in an autosomal recessive pattern, caused by mutations in genes involved in ciliary function, which may result in an end stage renal failure. "Here, we describe the case of a child who presented to the clinic with febrile convulsions and who was ultimately diagnosed with nephronophthisis caused by a homozygous deletion of the NPHP1 gene." (PMID 40620856, 2025). "An oligogenic inheritance has been suggested in several extra-renal involvements, like the NPHP1-associated retinopathy and Joubert syndrome, and even in less frequent subtypes of nephronophthisis itself." (PMID 38051388, 2024). "Biallelic pathogenic variants in NPHP1 are the most common cause of infantile nephronophthisis, and homozygous whole-gene deletions typically account for 25% of all NPHP1 pathogenic variants." (PMID 39669628, 2024). "A tailored copy-number variations analysis of genome sequencing trio data shows that biallelic inherited gene deletions are rare, with NPHP1 biallelic deletions causing nephronophthisis the leading finding." (PMID 39669628, 2024). "For example, detection of a pathogenic variant in the NPHP1 gene established the diagnosis of nephronophthisis in a child suspected of FSGS progressed to ESKD (case 5)." (PMID 37464296, 2023). "Over thirty genes are associated with nephronophthisis; nephrocystin-1 (NPHP1) accounts for 20% of cases and other genes < 3% each." (PMID 37628633, 2023). "Mutations in NPHP1 are associated with Joubert syndrome accompanied by renal dysfunction, accounting for the majority of cases of nephronophthisis." (PMID 37547536, 2023). "Nephrocystin (NPHP1) is a ciliary transition zone protein and its ablation causes nephronophthisis (NPHP) with partially penetrant retinal dystrophy." (PMID 33961633, 2021). "Full gene deletions of NPHP1 are associated with nephronophthisis, the most common genetic cause for ESRD in children." (PMID 31921302, 2019). "Like NPHP4, human mutations in NPHP1 are associated with multiple ciliopathies, including nephronophthisis and Joubert syndrome, characterized by cerebellar vermis hypoplasia." (PMID 26540106, 2015). "Later, it became apparent that NPHP1 is not only mutated in isolated nephronophthisis, but that a significant number of patients with NPHP1 mutations also display neurological symptoms." (PMID 22829176, 2013). "In 1997, the first genetic cause of nephronophthisis was identified through the detection of a deletion that covered the NPHP1 gene." (PMID 22829176, 2013). "Nephrocystin-1 (NPHP1) is a ciliary protein; loss of NPHP1 in humans causes nephronophthisis (NPH), an autosomal-recessive cystic kidney disease." (PMID 22701722, 2012). "NPHP1 is the product of a gene that is mutated in a different form of renal cystic disease, nephronophthisis (NPHP)." (PMID 20856870, 2010). "Our results show that PC-1, the product of the gene mutated in the most common form of PKD, interacts with NPHP1, the gene product of the NPHP1 gene, which is mutated in an unrelated cystic kidney disease, nephronophthisis (NPHP)." (PMID 20856870, 2010). "Interestingly, TNS1 has previously been shown to interact with NPHP1, a causal gene underlying a second cystic renal disease, nephronophthisis." (PMID 32513820, 2020). "Thus, we have hypothesized that disease modeling for juvenile nephronophthisis can be established using kidney organoids generated from patient-derived and gene-edited hiPSCs carrying NPHP1 deficiency." (PMID 38989059, 2024). "NPHP1, locating at 2q13, complete deletion of this gene might cause nephronophthisis." (PMID 32132867, 2020). "With respect to nephronophthisis, NPHP1 is the most commonly mutated gene, as genetic defects in this gene explain the cause of disease in 20% of patients with this disorder, while all other nephronophthisis-associated genes have been found to be mutated with a much lower frequency." (PMID 22829176, 2013).
nephronophthisis (continued). "Initial treatments included immunosuppressive therapy unless genetic testing with exome sequencing identified nephronophthisis due to a homozygous deletion of the NPHP1 gene, marking a unique instance of granulomatous nephropathy related to nephronophthisis." (PMID 40102251, 2025). "Feng Chen mentioned that the clinical diagnosis of atypical NPHP is challenging, proposed NPHP1 deletion in Chinese twins with nephronophthisis, and demonstrated in the text the superiority of whole exome sequencing (WES) for diagnosing this type of disease." (PMID 40620856, 2025). "In this study, we applied an IF-based approach to a large cohort of 111 individuals with either nephronophthisis (n = 58) or other renal ciliopathies (n = 53) using antibodies directed against NPHP1 and NPHP4." (PMID 39098869, 2024). "In our previous study, we generated and characterized two juvenile nephronophthisis-specific hiPSC lines derived from two patients carrying deletions spanning the whole NPHP1 gene." (PMID 38989059, 2024). "The clinical phenotypes in our NPHP1 deletion probands were consistent with those expected, including kidney failure secondary to nephronophthisis and retinal dystrophy, the combination of which is called Senior-Løken syndrome." (PMID 39669628, 2024). "In 25% of isolated nephronophthisis cases, a large genetic deletion arises from homologous recombination of genetic repeats, resulting in deletion of 290 kb and the entire NPHP1 gene (83 kb)." (PMID 37628633, 2023). "For example, PALS1-interacting proteins Nephrocystin-1 (NPHP1) and NPHP4 have been associated with nephronophthisis (NPHP), an autosomal recessive ciliopathic childhood cystic kidney disease." (PMID 35265622, 2022). "Nephronophthisis (NPHP) is an autosomal recessive hereditary disease with highly variable clinical characteristics for which 20 genes (NPHP1–20) have been identified." (PMID 31096956, 2019). "More recently, it has been reported that mutations in Abelson helper integration site 1 protein homolog (AHI1), which interacts with NPHP1, act as modifier of retinal degeneration phenotype in nephronophthisis." (PMID 20664800, 2010). "We show that PC-1 interacts with the SH3 domain of Nephrocystin-1 (NPHP1), the product of the NPHP1 gene mutated in nephronophthisis, an autosomal recessive disease characterized by a small cyst formation at the corticomedullary junction of the kidney." (PMID 20856870, 2010). "Nephrocystins are responsible for a hereditary cystic kidney disease, nephronophthisis, and to date, nephrocystin 1 (NPHP1) through nephrocystin 4 (NPHP4) have been identified." (PMID 15693946, 2005). "Nephronophthisis (1 NPHP1, 1 NPHP4, and 1 TTC21B found in our study) may also be a differential diagnosis of ADTKD in young adults; however usually, autosomal recessive inheritance distinguishes it from ADTKD." (PMID 38707821, 2024). "Also, it will be interesting to examine the role of other NPHP proteins that interact with NPHP1 protein using hiPSC-derived models with genome editing technologies for understanding the genetic heterogeneity of the nephronophthisis." (PMID 38989059, 2024). "In this case, sequencing and MLPA analysis of NPHP1 was also performed, together with the sequence analysis of other rarer genes related to nephronophthisis (INVS, NPHP3, NPHP4, IQCB1): no pathogenic variant was found in these genes." (PMID 37372410, 2023). "In a cohort of patients with nephronophthisis and neurological phenotypes consistent with Joubert syndrome (JBTS), half of those with variants in NPHP1 also harboured a second variant, including heterozygous missense variants in AHI1 and truncating variants in CEP290." (PMID 37628633, 2023). "In addition, we identified a disease-causing deletion in NPHP1 [MIM# 607100; gene previously associated with nephronophthisis (NPHP)] in one family (5% of solved families, 3% of all families)." (PMID 36245711, 2022).
nephronophthisis (continued). "In addition to marked differences in the age of onset, patients homozygous for NPHP1 deletions can vary dramatically in their phenotype, from isolated nephronophthisis with progressive CKD to Senior–Løken syndrome (SLSN), Bardet–Biedl syndrome (BBS), and mild forms of JBTS." (PMID 37628633, 2023). "NPHP1 deletion seems to be the main variation in NPHP genes, diagnosed in 20% of patients with nephronophthisis with a genetic diagnosis." (PMID 40102251, 2025). "In the present study, we focused on the putative roles of nephrocystins NPHP1 and NPHP4, two proteins involved in nephronophthisis, in the processes of flow sensation." (PMID 37916190, 2023). "Of the 26 patients with a full NPHP1 gene deletion, only 3 had a correct clinical PRD diagnosis of nephronophthisis." (PMID 31921302, 2019). "In previous studies, primary epithelial cells and tissues in juvenile nephronophthisis patients and mice disease models lacking NPHP1 have abnormally prolonged cilia and little number of ciliated cells." (PMID 38989059, 2024). "In the case of the transition zone complex components, Nphp4 and Nphp1 null mutant mice display male infertility without kidney phenotypes, in contrast to the human disease in which patients have severe nephronophthisis." (PMID 24415959, 2013).
ciliopathy (26 papers, 2009 to 2025). A genetic disorder of the cellular cilia or the cilia anchoring structures, the basal bodies, or of ciliary function. "SLS is a genetically heterogeneous renal–retinal ciliopathy associated with multiple ciliopathy-related genes, including NPHP1, NPHP4, IQCB1, and SDCCAG8." (PMID 40725491, 2025). "Fifty-seven ciliopathy patients with NPHP1 biallelic pathogenic variants were followed at Necker Hospital with sufficient phenotypic information." (PMID 38336713, 2024). "A gene set enrichment analysis (GSEA) performed on the entire set of transcriptome data identified that the genes related to ciliopathies were negatively enriched in the NPHP1-deficient group." (PMID 38989059, 2024). "GSEA and GOA analyses validate the dysregulation of genes related to ciliopathies and epithelial cilium movement in NPHP1-deficient kidney organoids." (PMID 38989059, 2024). "To evaluate the meaning of the protein axis Nphp4‐Invs‐Nphp1 in the development of ciliopathies caused by mutations in Rpgrip1l, we investigated the phenotype of Nphp4−/− mouse embryos." (PMID 29650680, 2018). "We also observed Wdpcp-deficient cells with mislocalization of Nphp1, a cilia transition zone protein required for ciliogenesis and associated with cystic kidney defects in Joubert syndrome and other ciliopathies." (PMID 24302887, 2013). "The homozygous deletion of a 250 Kb genomic region encompassing the NPHP1 gene is known to cause a group of ciliopathies including isolated juvenile NPH, Senior-Löken syndrome (NPH associated with retinal dystrophy), and JSRD with NPH." (PMID 21651769, 2011). "NPHP1 deficiency or mutation also causes ciliopathies such as JBTS, NPHP or BBS43–48." (PMID 29725084, 2018). "In particular, since retinal disorders are known complications with juvenile nephronophthisis, our disease modeling system using NPHP1-hiPSCs can apply to many other ciliopathies such as eye disorders." (PMID 38989059, 2024). "Such a data-driven approach aims at identifying patients with NPHP1 ciliopathy from large-scale clinical databases containing both rare and common diseases." (PMID 38336713, 2024). "Our objective was to develop a supervised machine learning pipeline for the detection of NPHP1 ciliopathy patients from a large number of nephrology patients using electronic health records (EHRs)." (PMID 38336713, 2024). "Deletions of NPHP1 are the most frequent cause of NPH, a pediatric ciliopathy and kidney disease that is characterized by tubular atrophy, cyst formation, interstitial fibrosis, and inflammation." (PMID 36460631, 2022). "We also found the most common pathogenic genes, NPHP1 and NPHP3, which were carried by 52% of Chinese children with NPHP-related ciliopathies." (PMID 36939782, 2021). "Positional cloning of nine responsible genes (NPHP1-9) has revealed NPHP as a “ciliopathy”, relating its pathogenesis to dysfunction of primary cilia signaling." (PMID 19165332, 2009). "The patients classified as potentially having NPHP1 ciliopathy could then undergo genetic testing for diagnosis confirmation and be eligible for potential future treatment." (PMID 38336713, 2024). "However, despite the absence of MTS and other phenotypes associated with ciliopathies, based on the phenotypic characteristics of the NPHP1 variation, case 10 could not completely rule out JS." (PMID 36468023, 2022). "In addition, the extreme genetic heterogeneity in NPH-related ciliopathies, i.e., the absence of mutation hot spots except for the homozygous NPHP1 deletion, and possible role of modifier variants, limit the practical and financial feasibility of gene-targeted therapies." (PMID 34055783, 2021). "We also observed that knockdown of ciliopathy genes ALMS1, BUBR1 [BUB1B], IFT80, NPHP1, NPHP8 [RPGRIP1L], TCTN2, TMEM216 and TUB retarded neuronal migration." (PMID 26206566, 2015).
ciliopathy (continued). "At least two polymorphic markers per gene (rs1718031 and rs729386 for NPHP1; rs1041480 and rs2064430 for AHI1; rs2061589 and rs1508595 for CEP290; rs1990637 and rs1946155 for RPGRIP1L; rs1483457 and rs911 for TMEM67) were inconsistent with linkage in Ciliopathy-672." (PMID 22002901, 2011).
Joubert syndrome (19 papers, 2013 to 2024). Joubert syndrome (JS) is characterized by congenital malformation of the brainstem and agenesis or hypoplasia of the cerebellar vermis leading to an abnormal respiratory pattern, nystagmus, hypotonia, ataxia, and delay in achieving motor milestones. "In the past, it was thought that CPLANE1 interacted with the NPHP1 gene in the primary ciliary transition region to cause the occurrence of Joubert syndrome." (PMID 35582950, 2022). "Disorders related to the homozygous or compound heterozygous deletions and loss-of-function mutations in NPHP1, such as Joubert Syndrome or Senior-Loken syndrome, have been linked to autism spectrum disorder, all of which can be found in disease community." (PMID 31044086, 2019). "Defects in NPHP1 can cause Joubert syndrome [MIM:609583], juvenile nephronophthisis [MIM:256100], and Senior-Loken syndrome [MIM:266900], which all have renal abnormalities." (PMID 27788217, 2016). "Nephronophthisis 1 (NPHP1) was another strong candidate gene that was identified and is associated with juvenile nephronophthisis and Joubert Syndrome (JS)." (PMID 26830357, 2016). "The TRMT44 gene is associated with partial epilepsy with pericentric spikes, and the NPHP1 is associated with Joubert's syndrome, which can alter the nuclei of the medulla oblongata in addition to the base of the pons, causing various neuropathological changes." (PMID 37884635, 2023). "For example, HNF1B mutations are associated with diabetes mellitus, and NPHP1 genetic variants may cause multisystemic diseases and Joubert syndrome, among others." (PMID 34295353, 2021). "In addition, a patient with Joubert syndrome caused by NPHP1 mutations (34:73) reported muscle cramps after NPH was diagnosed." (PMID 29974258, 2018). "Biallelic mutations in NPHP1 were detected in patients with isolated NPH (n = 12), Joubert syndrome (n = 2), and Senior-Løken syndrome (n = 2)." (PMID 29974258, 2018). "None of the eighteen genes is currently associated with human disease in the OMIM database except for NPHP1 which causes autosomal recessive nephronophthisis with or without Joubert syndrome that are not consistent with this patient’s features." (PMID 38565639, 2024). "WES coverage data might, in some cases, enable the detection of gene deletion: NPHP1 gene coverage was for instance equal to zero in patient P67 who presented with Joubert syndrome." (PMID 30665423, 2019).